CASP8 (caspase 8)
Diseases named in the same sentence as CASP8 in open-access papers (continued):
Sharing a sentence is not in itself a finding about the gene and the disease.
tumor (continued). "Additionally, increased levels of cleaved caspase 3 and 9 but not cleaved caspase 8 were observed in tumour tissues from the αCD7/EVs/CytC/siBcl2 group." (PMID 39676736, 2024). "In contrast to the Krt76−/− model, in which increased tumor incidence was not due to epithelial barrier malfunction but to an accumulation of Tregs in the oral epithelium, the Casp8−/− mouse model showed defective epithelial barrier formation and an immune infiltrate enriched in neutrophils." (PMID 39625985, 2024). "However, in another study, when the CRISPR-treated tumor cells were treated with cytotoxic T cells, Casp8 knockout tumors were not identified." (PMID 36635765, 2023). "Based on histopathological observations of colon tissue, tumor development was inhibited along with BRB administration, which was also characterized by decreased cell proliferation, and induction of the apoptotic pathways (caspase-3 and caspase-8) in the colon of BALB/c mice." (PMID 37576300, 2023). "Most of the literature examining Caspase-8 non-canonical roles has so far focused mainly on the Src kinase-mediated phosphorylation on Tyr380 as the principal mechanism responsible for switching Caspase-8 fate from an apoptotic protein to a tumor helper." (PMID 37444381, 2023). "Selenium plays an important role in increasing the expression levels of Caspase-1, Caspase-3, Caspase-8, and Caspase-9 and decreasing the expression levels of Bcl-2 and LC3, which promote the development of cellular pyroptosis and apoptosis and increase the rate of tumor cell death." (PMID 37994159, 2023). "FIS increases the cleavage of caspase-8 and caspase-3 and the expression of cytochrome C. Surprisingly, treatment with FIS causes a higher level of cytochrome C release in chemotherapy-resistant cells than in nonresistant tumor cells." (PMID 35807785, 2022). "It is possible that the high expression of caspase-8 in tumors results in a low level of residual caspase-8 activation that cleaves enough BID to induce minority MOMP and DNA damage, leading to tumorigenesis, while full caspase-8 activation would lead to apoptosis and tumor cell removal." (PMID 35741016, 2022). "As tumor targets, we used the reporter HeLa cell line stably transduced with the NES-ELQTD-GFP-T2A-NES-VGPD-mCherry construct, leading to the equimolar expression of two fluorescent reporters: Granzyme B-sensitive nuclear export signal (NES) fused to mCherry and Caspase-8-sensitive NES fused to GFP." (PMID 35300331, 2022). "In different two-dimensional (2D) tumor cell systems, sustained ER stress by misfolded or unfolded protein accumulation in the ER induces the PERK/ATF4/CHOP/TRAIL-R2/DR5-dependent and TRAIL-independent intracellular DISC assembly that activates a caspase-8-mediated apoptotic pathway." (PMID 35115486, 2022). "Given the importance of cFLIP proteins in the control of DISC-mediated caspase-8 activation upon extracellular TRAIL binding to TRAIL receptors, we have examined the role of cFLIP as a modulator of the protein-folding checkpoint in tumor cells under irreversible ER stress conditions." (PMID 35115486, 2022). "Interestingly, DOX induction of WT or MT caspase-8 did not result in a statistically significant alteration of tumor growth." (PMID 34362880, 2021). "Select chemotherapeutic agents have also been described to activate caspase-8-dependent GSDMC activation in tumor cells, or GSDMD activation in myeloid cells, however, whether myeloid GSDMD activation promotes or dampens tumor growth in vivo remains unclear." (PMID 33868312, 2021).
tumor (continued). "In addition to the enrichment analysis, using a maximum-likelihood dN/dS method we detected signals of positive selection for mutations within CASP8 and HRAS in samples with TMD, but not in expanding tumor samples." (PMID 34307377, 2021). "Our in vivo findings with a representative chemokine/cytokine-inducing mutant (D303G) suggest that some caspase-8 mutants, like WT caspase-8, may impact the immune composition of the HNSCC tumor microenvironment, presumably via modulation of the chemokine/cytokine milieu." (PMID 34362880, 2021). "Moreover, KC disappearance associated with caspase-1 activity induced the recruitment of monocyte-derived cells that are beneficial for tumor growth, while caspase-8-dependent reduction did not." (PMID 33178579, 2020). "The fact that we observed caspase-8 activity but no caspase-1 induction in KC following PH in animals without tumor might hint toward an analogous regulation in KC." (PMID 33178579, 2020). "Although previous reports have demonstrated that SMAC mimetics alone or in combination with radiation can suppress tumor cell growth in CASP8 WT HNSCC through induction of apoptosis, we did not identify a large apoptotic component in most of the cell lines we analyzed." (PMID 33108350, 2020). "Consistent with the GSEA results, CASP8-MT cases showed significantly higher infiltration of CD8+ T cells, neutrophils, and dendritic cells as compared to CASP8-WT cases (p-values < 0.0005), suggesting that the immune response to the tumor in WT and MT cases was different." (PMID 30775178, 2019). "Notably, in this tumor entity for both PLK3 and pT273 caspase-8 signals a significant positive correlation to the extent of HPV infection was evident with quantitative HPV viral load and p16INK4a expression to further correlate to local control as well as patients overall survival." (PMID 31475104, 2019). "In addition, our microarray and bioinformatic analysis demonstrated that USP39 regulated diverse cellular signaling pathways that were involved in tumor biology, and several pivotal genes (IRF1, Caspase 8, and SP1) have been validated by quantitative real-time polymerase chain reaction." (PMID 30898977, 2019). "Similarly, exposure of cells and tumours with USMB in vivo and in vitro have demonstrated enhanced tumour inhibition via regulation of Bax and Bcl-2 along with increased expression of cell-death related caspase-3, cleaved caspase-3, and caspase-8." (PMID 31851698, 2019). "Another reason for the lack of survival advantage in CASP8-MT HNSCs could be the composition of tumor-infiltrating immune cells in these tumors." (PMID 30775178, 2019). "Moreover, continuous exposure to sublethal concentrations of TRAIL induces an NFkB-dependent increase in miR-21, miR-30c and miR-100, which downregulates expression of caspase 8, caspase 3, TRAF7 and Foxo3a, resulting in acquired resistance to TRAIL and the development of more aggressive tumours." (PMID 27140313, 2016). "Similarly, it has been demonstrated that TRAIL; via caspase-8-mediated functions, and IL-12; via IFN-γ-dependent and T-cells-independent pathways, negatively regulates VEGF-induced angiogenesis and markedly decrease blood vessel formation in the tumor tissues." (PMID 27154307, 2016). "Functionally, stable overexpression of BM742401 resulted in inhibition of cellular proliferation and enhanced apoptosis through caspase-9-dependent intrinsic but not caspase-8-dependent extrinsic apoptosis pathway, suggesting a tumor suppressor role of BM742401 in CLL." (PMID 27689399, 2016). "Interestingly, in tumor tissue, but not in normal hepatocytes, caspase-8 showed a strong nuclear staining." (PMID 24209510, 2013).
tumor (continued). "First, PDT can activate caspase-8 and caspase-9, and then the active form of caspase-8 and caspase-9 initiates caspase-3 and caspase-6 activation to subsequently activate the remainder of the caspase cascade, which degrades PARP, and finally leads to apoptosis of tumor cells." (PMID 24204937, 2013). "Interestingly, in our cohort, high nuclear expression of caspase-8 correlated with a higher proliferation index of tumor cells (Ki67, r = 0.282, p = 0.0004, whereas the cytosolic expression of caspase-8 did not (r = 0.089, p = 0.274)." (PMID 24209510, 2013). "Due to the strong correlation between nuclear expression of caspase-8 and tumor grading, multivariate Cox regression analysis could not detect an influence of nuclear caspase-8 on survival independent from the tumor grade." (PMID 24209510, 2013). "As sensitisation of tumour cells to TRAIL can be achieved by downregulating XIAP, we asked whether a similar response could be induced in Me1007 cells, in spite of their low expression of caspase-8." (PMID 20461078, 2010). "Recently, multiple reports indicated that tumor cell death induced by multiple, chemically distinct SMAC mimetics was in fact dependent on the proteasomal degradation of multiple members of the IAP family and subsequent induction of TNFα production and caspase-8 mediated death." (PMID 20067634, 2010). "Repression of caspase-8 reduces metastasis without affecting the primary tumor." (PMID 19898689, 2009). "We examined apoptosis-inductive signalling in tumour cell death, and neither activation of caspase-9 via the mitochondrial system nor activation of caspase-8 via the cytoplasmic system, known as representative apoptotic signalling systems, were confirmed (data not shown)." (PMID 18087283, 2008). "Additionally, tumor‐infiltrating NK cells expressed lower Casp8 levels than normal tissues." (PMID 33934451, 2021). "Previous studies did not explore how caspase-8 and its functions regulated, particularly the determinant which switches caspase-8-mediated essential effects from pro-apoptosis to pro-survival to promote tumor growth remained unknown." (PMID 34482382, 2021). "Previous studies have shown that several biologically active substances could induce tumor cell apoptosis, inhibiting tumor progression by modulating pro-apoptotic proteins and apoptotic proteins (Bax, Bcl-xl) and increasing caspase expression and activation (CASP3, CASP8, CASP9)." (PMID 32381120, 2020). "Since CASP8 is an important mediator of the extrinsic apoptotic pathway, CASP8-MT tumors may have greater resistance to Fas- or DR5- mediated cell death pathways, which are typically employed by CD8+ T cells and Natural Killer cells to target infected/tumor cells." (PMID 30775178, 2019). "Cleaved caspase 1 (p20) (P < 0.05), cleaved caspase 3 (p17, 19) (P < 0.01), cleaved caspase 8 (p18, 43) (P < 0.05), cleaved caspase 9 (p37, 39) (P < 0.05), and TNF-stimulated gene 6 protein (TSG6) (P < 0.05) could be significantly identified in Sal-YB1-treated tumor mass by Western blotting." (PMID 26286454, 2015). "The TUNEL staining assay indicated that the blockages of P2X7 and especially caspase-8 could significantly inhibit the apoptotic process induced by the cryoablated tumor extracts in GL261 cells, while caspase-9 blockage did not affect the apoptosis-triggering effects of these extracts." (PMID 24818132, 2014). "However, using a cleavage-specific antibody for caspase-8, we could not detect activated caspase-8 in the nuclei of tumor cells in our cohort." (PMID 24209510, 2013). "Thus, it is intriguing to speculate that restoring IGFBP3 expression and/or use of demethylating drugs could contribute to new therapeutic strategies for HB, especially with the existence of additional epigenetically silenced genes in this tumor type, such as HHIP, RASSF1, SOCS1, APC and CASP8." (PMID 22401581, 2012).
tumor (continued). "Thus, absence of caspase-8 may become important at later tumor stages and may not be critical for growth of the primary tumor." (PMID 24281211, 2010). "Junwei Hou showed that PD-L1 under hypoxia switched TNFα-derived-apoptosis to pyroptosis mediated by noncanonical caspase-8 in MDA-MB-231 and 4T1 cells, eventually contributes to tumor necrosis." (PMID 36119049, 2022). "MAP3K14 (NIK1), BIRC2 (cIAP1), RIPK1, CASP7, CASP8, and TNF play an important role in inhibiting proliferation and invasion of tumor cells via the activation of the non-canonical NF-κB signaling pathway." (PMID 34638912, 2021). "On the one hand, the presence or lack of caspase-8 in the tumor is essential for the secretion of soluble factors in the TME, which regulate the immune system, tumor growth, angiogenesis, and metastases." (PMID 33026575, 2021). "We found that there was no change of the active caspase-8 expression in cells treated with DHA at 24 h, 48 h and 72 h, suggesting that the extrinsic apoptotic pathway was not involved in the anti-tumor activity of DHA." (PMID 29033794, 2017). "As a consequence, we observed reduced caspase-8 or DR4 expression which clearly explains how TRAIL generated signals are not at all, or less efficiently transduced, and how these tumor cells escape death receptor-induced apoptosis." (PMID 24618889, 2014). "To investigate the relationships between SLIT2 promoter methylation and de novo methylation of RASSF1A and CASP8, we compared the frequencies of CASP8 and RASSF1A methylation in tumours with and without SLIT2 methylation." (PMID 14735202, 2004). "In tumours without SLIT2 methylation, CASP8 and RASSF1A promoter methylation was detected in 39% (nine out of 23) and 70% (16 out of 23), respectively." (PMID 14735202, 2004). "Our results demonstrate that when tumor cells are grown in the absence of glutamine, stimulation of the GCN2/ATF4/CHOP pathway results in TRAIL-R2 upregulation, an important event leading to caspase-8 activation and apoptosis." (PMID 36302756, 2022). "Immunohistochemical results suggested that in tumor tissues, CASP8 and SAMSN1 showed high staining, TXNIP showed medium staining, while KLF6 and XCL1 showed negative staining; in normal tissues, KLF6 showed medium staining, CASP8 and SAMSN1 showed low staining, while TXNIP showed negative staining." (PMID 40149637, 2025). "However, the non-canonical elevation of Casp8 expression we observed in CAL27 cells following STAT1 inhibition warrants further investigation, as this may be a driver behind tumour survival in cases of HNSCC with high expression of STAT1." (PMID 35595823, 2022). "The high levels of TNF-α, the accumulation of receptor-interacting protein kinase-3 (RIP3K) and its lack of cleavage by Caspase-8 in mice injected with HepG2/SB3 provide evidence of necroptotic death in this experimental model, highlighting its protective function in slowing down tumor growth." (PMID 33922660, 2021).
infection (249 papers, 2004 to 2026). The state of being infected such as from the introduction of a foreign agent such as serum, vaccine, antigenic substance or organism. "Necroptosis can proceed as an alternative to extrinsic apoptosis when caspase-8 activity is compromised during infection with cytomegaloviruses that utilize homologous virus-encoded cell death suppressors." (PMID 41011779, 2025). "CpG sites linked to Ccl7, Ccl9, Cd74, and Casp8 exhibited the lowest methylation in uninfected samples but increased on Day 1 of infection and then decreased gradually." (PMID 40170749, 2025). "This notion was further supported by in vitro studies where induction of Casp8 deletion by infection of Casp8fx/fx HSPCs with Cre-expressing virus also caused massive cell death." (PMID 38637559, 2024). "Strikingly, C. rodentium-infected Casp8–/–Ripk3–/–Casp1/11–/– mice showed severe body weight loss and died within 12 dpi, while the other cohorts survived the infection." (PMID 37080966, 2023). "We found that Casp1/11+/–Casp8–/–Ripk3–/– mice largely phenocopied WT B6 mice, and were resistant to infection, exhibiting minimal weight loss, diarrhea, cecal or colonic shrinkage, and no fecal blood." (PMID 36645406, 2023). "We do observe that Casp1/11–/–Casp8+/–Ripk3–/– are modestly susceptible to infection while Casp1/11+/–Casp8–/–Ripk3–/– mice are fully resistant." (PMID 36645406, 2023). "The specific process of NCPS involves activation of RIP1 by TNF-α/TNFR1 when caspase-8 is cleared or inhibited by mutation or infection and the subsequent recruitment of RIP3 through the RIP homotypic interaction motif (RHIM)." (PMID 35892430, 2022). "Casp8/Ripk3/Casp1/11−/− mice were significantly more susceptible to lethal infection with WT B. thailandensis than were WT mice." (PMID 34154417, 2021). "Surprisingly, TNF-driven death during vMIA/vIBO-deficient mutant infection occurs independently of CASP8 and despite the presence of virus-encoded vICA." (PMID 34578288, 2021). "We stained caspase-8 in macrophages transduced with retrovirus encoding ASC-GFP and found that caspase-8 colocalized with ASC puncta in response to infection with flagellated bacteria." (PMID 28771586, 2017). "Analysis of caspase 8 activation by flow cytometry of A549 cells showed that none of the viruses caused measurably increased levels during days 1–2 post-infection, but Ad5-treated cells showed activation of caspase 8 day 3 post-infection." (PMID 28345021, 2017). "Notably, direct comparison of infection in C1/11/12/8/R3-/- and C1/11/12/R3-/- mice revealed that the additional deletion of caspase-8 resulted in a distinct upregulation of genes linked to pathogen killing and apoptotic processes." (PMID 41233351, 2025). "We suspect that caspase-8 could exert a similar apoptosis/autophagy regulating role in infections caused by viruses other than HSV-1." (PMID 36418547, 2023). "Caspase 8-mediated cell death induced by infection with pathogenic Yersinia spp." (PMID 37621095, 2023). "Casp1/11/8–/–Ripk3–/– mice, however, should lack the cell death pathways initiated by NLRC4 (via Caspase-1 or Caspase-8), Caspase-11, and TNFα, and our results above suggest that these mice might be highly susceptible to infection." (PMID 36645406, 2023). "Subsequent studies have shown that cells deficient in caspase-1/-11 or caspase-8/RIPK3 still undergo cell death in response to the infection, while cells deficient in caspase-1/-11/-8/RIPK3 or cells deficient in caspase-1/-11/-12/-8/RIPK3 are protected from cell death." (PMID 35563804, 2022). "Herein, reduced IL-1β secretion and pyroptosis observed in Casp8/RIPK3−/− mice are possible mechanisms that may contribute to increased susceptibility to infection." (PMID 36532444, 2022). "However, inhibition of the receptor-proximal signaling kinases TAK1 or IKK by chemotherapeutic drugs or during infection by bacterial pathogens such as Yersinia, can trigger a caspase-8-dependent apoptosis pathway that is also associated with GSDMD cleavage." (PMID 34648590, 2021).